IL6 (interleukin 6)
Diseases named in the same sentence as IL6 in open-access papers (continued):
Sharing a sentence is not in itself a finding about the gene and the disease.
infection (continued). "Rage−/− mice had lower TNF-α and IL-6 levels at 24 hours of infection and lower KC concentrations at 24 and 48 hours when compared with Wt mice." (PMID 24342460, 2013). "We have demonstrated previously that, unless overwhelming doses of Brucella are injected (>108 CFUs), TNF-α, IL-6 and IL/-10 cytokines seldom reach significant levels in serum at early times of infection." (PMID 23458832, 2013). "Maximum secretion was observed at 1 day (24 h) after RV14 infection for IL-6 and IL-8 and at 3 days (72 h) after infection for IL-1β." (PMID 24303127, 2013). "In the liver and the kidneys, the situation is different and Ank1Ity16/ity16 mice showed marked increases in Il1 (liver and kidneys) and Il6 (liver) mRNA expression during infection." (PMID 23390527, 2013). "TNFα and IL-6 levels were also comparable between the lungs of Nlrp12−/− and wild type mice at one day postinfection and during the chronic phase of the infection." (PMID 23577168, 2013). "In a control experiment, mice were immunized with Ad.IL5, Ad.IL6 or Ad.IL23 alone to exclude any direct effects of the cytokine vectors on subsequent FV challenge infection." (PMID 24349306, 2013). "While the induction of IL-6 was quite comparable in both infection groups, ΔdnsΔxds mutant infected mice exhibited a significant higher expression of MIP-2 and KC compared to wild type infected mice." (PMID 24039581, 2013). "Il6 mRNA increased in both strains beginning 6 h after infection or mock treatment, with stronger regulation being observed in the DBA/2J mice." (PMID 24341411, 2013). "Downstream of TNFα, IL-1β, and IL-6 other cytokines are released such as IL-8 that induce migration of neutrophils and phagocytes to the site of infection." (PMID 24391635, 2013). "Prior to infection, the mean serum concentration of IL-6 in all monkeys was 1.37 pg/mL (range: 1.12–1.43 pg/mL)." (PMID 24194772, 2013). "Mast cells produced higher levels of IL-6 in response to infection with the L. monocytogenes strain with a modified InlA suggesting that the interaction with E-cadherin potentiates cytokine and chemokine release." (PMID 23460827, 2013). "A similar profile has been demonstrated by Raida and Buchmann (2009) where IL-6 showed a significantly increase in fold changes at 8 h (4-fold), on days 1 (46-fold) and 3 (1100-fold) post infection, followed by a decrease in transcription levels." (PMID 24391635, 2013). "The pro-inflammatory cytokines IL-6 and IL-8 are produced by uroepithelial cells as part of the early immune response and are important for the clearance of the infection." (PMID 24059789, 2013). "As expected, the infection induced IL-1, IL-6, KC, TNF-α, IL-10, IL-12, and IFN-γ release at all time points compared with noninfected mice." (PMID 23818746, 2013). "Macrophages line the peritoneal cavity and have an autonomous 24-hour clock that regulates phagocytosis and the rhythmic secretion of TNF and IL-6 in response to infection, with peak activity late in the day." (PMID 24160251, 2013). "Specifically, it has been shown that mast cell-derived IL-6 is a major mediator of survival from severe infections by enhancing intracellular killing of bacteria by neutrophils." (PMID 23637741, 2013). "In the Jak-STAT signalling pathway 12.4% of the genes were differentially expressed at the beginning of infection, including greatly increased expression (>10 fold) of IL6, IL7R, IL11 and IL20." (PMID 23326599, 2013). "Taking mock-infected fish as a reference, expression of several cytokines (IFN-γ2, IL-1β, IL-6, and IL-10) was up-regulated as early as day 3 post-infection." (PMID 23865540, 2013). "Inflammatory cytokines, including TNF-α, IL-1β and IL-6, can be released by activation of mononuclear macrophages after severe trauma, infection and shock." (PMID 24039865, 2013). "The kinetics of TNF-α, CXCL1, IFN-γ and IL-6 showed a similar time dependent increasing trend with peak expression at 72h of L2-MHV3 infection." (PMID 24058536, 2013).
infection (continued). "Expression of pERK, which acts downstream of Kras and is associated with cancer cell proliferation, was reduced in tumors from KrasG12D; IL-6-/- mice 20 weeks post-infection with adeno-Cre compared to KrasG12D mice." (PMID 24260500, 2013). "The levels of interleukin-6 (IL-6) and interferon-gamma in the bronchoalveolar lavage fluids after infection were significantly decreased in offspring mice exposed to methamidophos." (PMID 24369005, 2013). "Infection of human monocytes with either UV-inactivated RSV or RSV F protein results in increased production of IL-6, TNF-α and IL-β which is mediated via TLR 4 activation." (PMID 24244872, 2013). "Previously, studies examining the lack of activation/active suppression of inflammation by Francisella have been primarily focused on a limited set of well-known mediators, such as TNFα, IL6, IL1β, etc, as a measurement of immune response to infection." (PMID 23690939, 2013). "Serum IL-6 concentration was significantly higher (P < 0.001) on day 10 after infection in mice that received the combined treatment, when compared with mice treated with AmB alone." (PMID 24106515, 2013). "Infection of Calu-3 cells with either virus induced HRV-associated increases in FGF-Basic, IL-15, IL-6, IL-28A, ENA-78 and IP-10." (PMID 23799120, 2013). "During infection, liver Hamp expression levels remain suppressed and Gdf15, Il1 and Il6 expression increased significantly in Ank1Ity16/Ity16 mutant mice compared to wild type littermates." (PMID 23390527, 2013). "H37Rv infection of neutrophils resulted in more than 38-fold increase in the production of IL-6 compared to uninfected neutrophils." (PMID 24312131, 2013). "To investigate differential inflammatory responses associated with Lmo-InlA-mur-lux and Lmo-EGD-lux infections, we measured serum levels of IFN-γ, IL-10, TNF-α, IL-6, CCL2, IL-5 and IL-1β at 3 and 5 days p.i. using Luminex bead arrays." (PMID 23617550, 2013). "Lytic reactivation of latent virus was also performed by incubating latently infected (18 days post infection) CD14 (+) monocytes with IL-6 and re-plating in tissue culture flasks that allowed for cell attachment." (PMID 23717203, 2013). "We observed at 14 hours post infection a statistically significant 40-fold increase in levels of IL-6 and TNF alpha, and a 4-fold increase in IL-1 beta compared to the mock treated mice." (PMID 23874613, 2013). "pERK expression was reduced in KrasG12D; IL-6-/- tumors 20 weeks post-infection, but increased in most KrasG12D; IL-6-/- tumors 32 weeks post-infection." (PMID 24260500, 2013). "RNA was then isolated from C57BL/6 and IL-6−/− corneas at 24 h post-infection, and gene expression was measured by Q-PCR." (PMID 23853581, 2013). "For Ad.IL5 and Ad.IL23, this improvement correlated with enhanced neutralizing antibody titers after FV challenge infection, whereas mice co-immunized with Ad.IL6 showed improved virus-specific CD4+ T cells." (PMID 24349306, 2013). "DCs induce production of numerous cytokines including TNFα, IL-6, IL-10, and IL-12 upon infection with Mtb in vitro." (PMID 24350246, 2013). "While we have previously shown that IL-17–producing CD4+ T (Th17) cells were barely detectable in LCMV-DOC infection, it remains possible that IL-21 inhibits Treg cell expansion by regulation of IL-6." (PMID 23696736, 2013). "In the context of neuropathic pain, it is important to mention that pro-inflammatory cytokines, of which IL-6 is the main one, also induce behavioral discomfort or ‘sickness’, not only in response to infection but also after nerve trauma." (PMID 23634725, 2013). "Consistent with the function of C16 inhibiting the innate immune response to DNA, this effect was significant in the first 2 d post infection (p.i.)at 24 and 48 h p.i. for Cxcl10, and at 24 h p.i. for Il-6." (PMID 24098118, 2013).
infection (continued). "In vivo infection with S. aureus caused significantly elevated production of TNF-α and IL-6 in the livers and blood of TLR2-deficient mice compared with those in WT mice, while the hepatic and serum levels of IL-10 decreased in these mice." (PMID 24058538, 2013). "Of note, IL-1β and IL-6 levels were consistently higher 8 h post infection in mice passively immunized with 2A3 compared to animals infected with Δhla." (PMID 24098366, 2013). "Infection of mice with VACV vΔC16 caused enhanced production of the chemokine Cxcl10 and the cytokine Il-6 in the lungs." (PMID 24098118, 2013). "In the event of intra-amniotic infection or choriodecidual space infection, inflammatory cytokines such as IL-1α, IL-1β, IL-6, IL-8, and granulocyte colony-stimulating factor are released." (PMID 23818902, 2013). "Predictors of infection-associated spontaneous preterm delivery include tumor necrosis factor-α (TNF-α), IL-6, IL-1, and IL-8." (PMID 23818902, 2013). "Infection with PAK significantly increased the pro-inflammatory cytokines TNF-α and IL-6 in BAL fluid from SP-A-/- compared to SP-+/+ mice 24 hours after infection." (PMID 24312669, 2013). "We have shown by in vitro experiments that primary Chlamydia infection of human epithelial cells and mouse macrophages occurs within 2 days of infection and is characterized by significant production of IL-6, TNF, and IL-8." (PMID 23766556, 2013). "The pro-inflammatory cytokines IL-6 and IL-1β were significantly lower, after infection, in the lung compartment of panobacumab-treated animals as compared to untreated animals." (PMID 24023870, 2013). "Th17 cells produce IL-17 which is capable of inducing expression of chemokines, such as G-CSF, CXC chemokines, IL-6, and IL-8 that promote Th1 cell recruitment and granuloma organization throughout infection." (PMID 23967337, 2013). "Regarding our results, interleukin 6 had the greatest value for predicting infection and possible mortality, whereas IL-8 was valuable for diagnosing definitive infection." (PMID 24570828, 2013). "TLR activation signals through the NF-κB pathway to up-regulate the transcription of proinflammatory cytokines, including IL-1β, TNFα, and IL-6, which are essential for the recruitment of leukocytes to the lung and clearance of the infection." (PMID 23577168, 2013). "The infection of CD1b+ L-DCs with Salmonella for 6h induced a significant increase in IL-1ß, IL-6, IL-12p40 and IL-10 mRNA, whereas only IL-6 mRNA increased after Hc-ES stimulation." (PMID 24223964, 2013). "The study shows that IL-6 in CSF is elevated in late-stage infection of HAT and is accompanied by a rise in WCC, total protein and reactive astrogliosis." (PMID 24194772, 2013). "Non-pathogenic M. smegmatis, as compared to pathogenic M. tuberculosis H37Ra and M. tuberculosis H37Rv, following infection, induced the PMs to elaborate highest (p < 0.001) amounts of IL-6 at all the time-points studied." (PMID 24455461, 2013). "IL-6 is a pleiotropic cytokine with key roles in infection, inflammation, autoimmunity and tissue haemostasis." (PMID 24688720, 2013). "Infection triggers the secretion of high levels of inflammatory cytokines including IL-6, IL-8 and TNFα in patient serum." (PMID 23359320, 2013). "IL-6 induces hepcidin expression and it is thought that the increase in circulating hepcidin during infection/inflammation is primarily mediated by IL-6." (PMID 23460869, 2013). "The IL-6 expression was higher in the children showing chronic stress, anoxia, and infection (P ≤ 0.001)." (PMID 23401697, 2013). "Significant increases in IL-8 and IL6- mRNA after infection with APP have previously been observed in lung lavage as well as lung tissue using northern blotting and in situ hybridization." (PMID 23698783, 2013).
infection (continued). "There are also publications about IL-17 secreting NK cells in a mouse infection model, where IL-17 secretion is IL-6 dependent." (PMID 24069246, 2013). "Significantly fewer labeled nuclei were observed in lung sections from KrasG12D; IL-6-/- mice 20 weeks post-infection with adeno-Cre compared with those derived from control KrasG12D mice." (PMID 24260500, 2013). "The concentration of IL-6 peaked at 36 h post Pm infection of mice and remained elevated for the longer period of time (at least to 96 h post infection)." (PMID 23332090, 2013). "Several of the mediators that are essential to the immune response and activation of lymphocytes can exacerbate infection and cause clinical symptoms when over produced in response to HHV-8 infection, including IFN-γ, IL-1β, IL-6, IL-8, TNF-α, and MCP-1." (PMID 23346088, 2012). "UL81-82ast transcripts were detected in FIX-WT, FIX-ΔLUNA and FIX-Rev infected CD14+ cells throughout the course of infection, including post IL6 induced differentiation." (PMID 23300789, 2012). "Recently, downregulation of let-7 family members was identified as control major regulators of inflammation, including IL-6 and IL-10 in macrophages and HeLa cells upon infection with Salmonella." (PMID 22312311, 2012). "Here, we report increased IL-6 expression in both humans hospitalized with H1N1pdm infection and in multiple mice strains infected with H1N1pdm (A/Mexico/4108/2009 (H1N1pdm)), which implicated IL-6 in the host response to H1N1pdm infection." (PMID 22679491, 2012). "Relatively high levels of TNFα, IFNγ, IL-1, IL-6 were recorded at the early stage of infection and persisted throughout." (PMID 23323093, 2012). "Detection of IL-8 and IL-6 in day-1 and-3 infected cell culture supernatants begin at 2 days after infection." (PMID 22529524, 2012). "In experimental infection with Theiler virus, TNF, IL-6 and associated inflammatory changes mainly contribute to the occurrence of acute seizures." (PMID 22848506, 2012). "Kinetics studies revealed that live C. trachomatis induced TNF, IL-6, and IL-8, as a function of time, with day-2 infection inducing the highest cytokine levels." (PMID 22529524, 2012). "IL-6 correlated positivity with the presence of infection and type of pathogen (P = 0.038 and 0.034 resp)." (PMID 23724320, 2012). "Consistent with clinical observations, we found that IL-6 was increased during the host response to H1N1pdm infection in mice." (PMID 22679491, 2012). "Here, the secreted designer cytokine was detectable also at 12 hpi and the hyper-IL-6 concentration increased during the infection." (PMID 22236378, 2012). "The levels of myeloperoxidase (as neutrophil marker), TNFα, INFγ, GM-CSF, IL-1β and IL-6 transiently increased in lungs after infection, while levels of IL-10, IL-17A and IL-22 were indistinguishable from PBS controls." (PMID 22319619, 2012). "Among the low-dose infected fish, only IL-6 was induced but at a lower level, 3.9-fold induction, SD = 4.8, compared to high-dose infection at 1 dpi." (PMID 23028333, 2012). "Pre-treatment of UV-inactivated CMV particles with antibodies against gB and gH prior to infection of human fibroblasts resulted in a 40–50% reduction in secreted IL-6, confirming the importance of the recognition of gB and gH by TLR2 during CMV infection." (PMID 23061052, 2012). "At 96 hours post introduction of infection, only the values for IL-6 were significantly greater in mothers that received experimental UTI compared to mothers in the sham cohort (p = 0.0028)." (PMID 22470490, 2012). "Infection of MΦ and DCs with live mycobacteria is generally associated with induction of a strong pro-inflammatory phenotype with production of TNF, IL-12 and IL-6 that in turn is accompanied by the regulatory response, including secretion of IL-10." (PMID 22880012, 2012).
infection (continued). "Infection of monocytes with Udorn also induced the release of IL-6, IL-8, TNFα and IP-10, suggesting that NS1 protein of Udorn does not (effectively) inhibit this host defence response in human monocytes." (PMID 22238612, 2012). "In contrast, RB51 demonstrated more than two-fold of increased production of IL-6 in WT BMDCs compared to the medium control or the S2308 infection group." (PMID 22927979, 2012). "The IL-6 concentrations did significantly increase CSF, brain homogenate and plasma 30 hours after infection." (PMID 22455545, 2012). "Administration of MSCs led to a 50% reduction in the expression of TNFα (p = 0.01), a 34% reduction of IL1β (p = 0.02) and a 60%reduction of IL6 (p = 0.006) 7 days after infection." (PMID 22815907, 2012). "Meanwhile, infection-induced increases in IL-6 production stimulate hepatocytes to synthesize and secrete acute-phase proteins such as CRP." (PMID 22934219, 2012). "When the magnitude of serum IL-6 was correlated to the weight of each individual fetus at 96 h post infection, the highest levels of IL-6 were observed in those infected mothers with the lowest weight offspring." (PMID 22470490, 2012). "After 30 minutes of S. Typhimurium SL1344(p1C/1) infection the supernatants from ESC derived DCs harbored IL-6, MCP-1 and TNFα." (PMID 23284947, 2012). "The IL-6 levels were significantly up-regulated in the db/db mice at days 6 and 8 after infection (p<0.05)." (PMID 22953001, 2012). "Inflammatory cascades are propagated by proximal mediators such as IL-6, which exerts pro-inflammatory effects including stimulation of the liver to produce positive acute-phase proteins during tissue injury or infection." (PMID 22970224, 2012). "This led us to investigate by functional genomics the impact of IL-6 on the inflammatory response during H1N1pdm infection." (PMID 22679491, 2012). "Airway levels of CXCL1, CCL2, CCL3, CCL5, IFNγ, IL-6, and TNFα were measured 3 and 6 days after infection." (PMID 22496659, 2012). "The cellular inflammatory response during severe RSV infection is characterized by a preponderance of neutrophils and macrophages, suggesting that the expression of IL-6 at the site of infection is an essential feature in disease progression." (PMID 22962966, 2012). "Taken together, these results suggested a consistent role for IL-6 in response to H1N1pdm infection at either 104 or 105 EID50." (PMID 22679491, 2012). "Bladder and kidney epithelial cells appear to be a major source of interleukin-6 (IL-6) and interleukin-8 (IL-8) after infection with UPEC, which are important in the development of local tissue damage." (PMID 22506110, 2012). "Infection of airway epithelial cells with rhMPV-ΔSH led to increased interleukin 6 (IL-6), IL-8, and MCP-1 secretion, compared to rhMPV-WT." (PMID 23223197, 2012). "The secretion of CXCL8 and IL-6 from infected epithelial cells was delayed and began 24 h of infection." (PMID 22058091, 2012). "Determination of IL-6 and TNF alpha in blood samples and homogenates of the cerebellum 30 hours after infection revealed that the protein expression of IL-6 was much higher in both compartments in comparison to TNF alpha." (PMID 22781194, 2012). "The improved survival in the P2X7R deficient mice correlated with diminished levels of IL-1β and IL-6 and reduced neutrophil infiltration in the early phase of infection." (PMID 22558229, 2012). "For example, we found peak induction of IL-1β and IL-12p40 mRNA in alveolar macrophages occurs on day 3 post-infection in the neonatal bRSV model, whereas IL-6 mRNA was higher at day 5 than day 3 of infection." (PMID 23342375, 2012). "Given the known involvement of IL-6 in pathogenic lung inflammation, we sought to investigate the role of IL-6 in severe H1N1pdm infection, and potential contributions to disease." (PMID 22679491, 2012). "In pDC-depleted mice, IL-12p40, IFN-γ, and IL-6 were all reduced at days 3 and 5 after infection compared with control animals." (PMID 23119083, 2012).